TG (thyroglobulin)
Diseases named in the same sentence as TG in open-access papers (continued):
Sharing a sentence is not in itself a finding about the gene and the disease.
gestational diabetes (7 papers, 2015 to 2026). Carbohydrate intolerance first diagnosed during pregnancy. "We have recently observed in a preliminary study that in a group of women with gestational diabetes mellitus (GDM), a disorder characterized by mild hyperglycemia, those that presented anti-thyroglobulin antibodies (aTgAbs) also had significantly higher HbA1c levels." (PMID 26229534, 2015).
hyperlipidemia (7 papers, 2015 to 2025). "Our study also concluded that lower LMR was significantly associated with the development of CLNM in patients with PTCI, but did not conclude that creatinine value, hyperlipidemia, thyroglobulin, and thyroid stimulating hormone were associated with CLNM." (PMID 37598343, 2023). "And there was statistically significant difference among the CKD and non-CKD in terms of age, sex, race, education levels, thyroglobulin (Tg), BMI, SBP, DBP, Urine iodine-group, hyperlipidemia or not, DM or not." (PMID 40783753, 2025).
lung carcinoma (7 papers, 2011 to 2022). "It was discovered as a transcriptional regulator of thyroglobulin in 1989, and the first studies in relation to lung cancer were conducted in 2007." (PMID 27992557, 2016).
melanoma (7 papers, 2018 to 2024). A malignant, usually aggressive tumor composed of atypical, neoplastic melanocytes. "The tumor cells were positive for AE1/AE3, S-100 protein, melan A, HMB-45, synaptophysin, calcitonin, chromogranin A, melanoma, and thyroid transcription factor-1 (TTF-1) and negative for thyroglobulin." (PMID 30424779, 2018).
multinodular goiter (7 papers, 2015 to 2025). Nodular goiter characterized by more than one discrete tissue mass. "Separate analysis of a subset of the multinodular goiter samples with more aggressive PTC subtypes revealed 2 - 4-fold upregulation in the levels of CHEK1, c-MET and TIMP1, and a 2-4-fold downregulation of BCL2, c-KIT, TG and PPARγ (lower part)." (PMID 25868389, 2015).
psoriasis (7 papers, 2013 to 2025). An autoimmune condition characterized by red, well-delineated plaques with silvery scales that are usually on the extensor surfaces and scalp. "For instance, anti-thyroid peroxidase antibodies (anti-TPO) and anti-thyroglobulin antibodies (anti-TG) are frequently observed in patients with AITDs and reflect a breakdown in immune tolerance, a mechanism also relevant in psoriasis pathogenesis." (PMID 40863211, 2025). "The mean value of anti-TPO Ab was also highly significant (p<0.001**), while anti-TG Ab levels were significantly higher in the psoriasis group than in the control group (p=0.004)." (PMID 38192953, 2023). "The mean values of anti-TPO Ab and anti-TG Ab were significantly higher in psoriasis subjects than in controls (p<0.001 for anti-TPO and 0.004 for anti-TG, respectively)." (PMID 38192953, 2023). "The role of early detection of anti-thyroid antibodies, i.e., anti-TPO Ab and anti-TG Ab, can be of prognostic value in AITD and psoriasis." (PMID 38192953, 2023). "The high degree of specific binding by psoriasis IgGs (immunoglobulin G) to ROS-epitopes-HSA, ROS-thyroid antigen, and ROS-thyroglobulin was observed." (PMID 33585138, 2021).
renal cell carcinoma (7 papers, 2011 to 2025). "They did not express CD30, α-fetoprotein, p63, placental alkaline phosphatase (PLAP), surfactant B, napsin-A, CD10, pax-8, thyroglobulin, or renal cell carcinoma." (PMID 25442640, 2014). "RCC: renal cell carcinoma; a-TPO: anti-thyroid peroxidase antibody; ATG: anti-thyroglobulin." (PMID 41487768, 2025). "In contrast, thyroid transcription factor 1 (TTF-1), anti-renal cell carcinoma (RCC), CD10, CK20, as well as synaptophysin, chromogranin A, thyroglobulin and transthyretin are negative." (PMID 35546652, 2022).
subacute thyroiditis (7 papers, 2014 to 2024). Self-limited inflammation of the thyroid gland characterized by the presence of multinucleated giant cells. "This case, presenting with a localized painful hot nodule, normal thyroid function, normal ESR, and normal serum thyroglobulin levels, is a rare case of subacute thyroiditis, which should be considered during differential diagnosis." (PMID 24397799, 2014). "This case demonstrates that subacute thyroiditis may present as a solitary painful hot nodule in conjunction with normal thyroid function, thyroglobulin levels, and ESR and should, therefore, be considered in the differential diagnosis of such lesions." (PMID 24397799, 2014). "In conclusion, this case demonstrates that subacute thyroiditis should be considered as a differential diagnosis following presentation with a solitary painful thyroid hot nodule in conjunction with normal thyroid function, thyroglobulin levels, and ESR." (PMID 24397799, 2014).
anaplastic cancer (6 papers, 2012 to 2022). "We speculated that our patient had a high titer of anti-thyroglobulin antibodies and that the tumor lost its ability to produce thyroglobulin because it transformed into undifferentiated carcinoma when the multiple lung and mediastinal metastases developed." (PMID 24407283, 2014). "Measuring the level of serum CA19-9 is meaningful in patients with positive anti-thyroglobulin antibodies and in those with transformation of PTC to undifferentiated carcinoma." (PMID 24407283, 2014). "Thyroglobulin and TTF-1 expression are lost in cases of anaplastic cancer." (PMID 35154933, 2022). "Thus, serum thyroglobulin is not a reliable marker for patients with a high titer of anti-thyroglobulin antibodies or in cases of transformation to undifferentiated carcinoma." (PMID 24407283, 2014).
Hashimoto encephalopathy (6 papers, 2017 to 2025). "Examinations for thyroid stimulating hormone (TSH) were normal, but the levels of microsomal antibodies and anti-thyroglobulin antibodies significantly increased, so the diagnosis of Hashimoto's encephalopathy was established after ruling out other causes." (PMID 30873174, 2019). "Hashimoto’s encephalopathy (HE) is a neurological condition associated with elevated anti-thyroid antibodies (anti-thyroglobulin or anti-thyroid peroxidase (TPO)), often occurring in euthyroid individuals." (PMID 29177818, 2017). "Because serum antithyroid antibody, anti-microsomal antibody, and thyroglobulin antibody were increased, Hashimoto’s encephalopathy could also be considered." (PMID 39967585, 2025). "In combination with his increased titers of anti-thyroglobulin antibodies, this patient might suffer from Hashimoto encephalopathy." (PMID 29212505, 2017).
hypoparathyroidism (6 papers, 2020 to 2025). Hypoparathyroidism is an endocrine disorder in which the parathyroid glands in the neck do not produce enough parathyroid hormone (PTH). "Post-operatively, the subject developed hypoparathyroidism-related hypocalcemia and showed a very high serum thyroglobulin level (>550 ng/mL)." (PMID 40870901, 2025). "The potential benefits of performing routine prophylactic CLND, such as better risk stratification of recurrence according to micrometastatic central lymph nodes and lower thyroglobulin levels after operation, should be balanced by the potential risks, such as permanent hypoparathyroidism." (PMID 33013682, 2020).
lung adenocarcinoma (6 papers, 2013 to 2025). A carcinoma that arises from the lung and is characterized by the presence of malignant glandular epithelial cells. "The immunostains TTF-1, thyroglobulin, PAX8, and Napsin-A are markers that are used in the differential diagnosis of PTC from primary lung adenocarcinoma." (PMID 27774331, 2016). "Immunohistochemical staining yielded positive results for thyroid transcription factor-1 (TTF-1) and napsin A and negative results for thyroglobulin, leading to the diagnosis of metastasis from lung adenocarcinoma." (PMID 37719531, 2023).
lymphoma (6 papers, 2014 to 2025). A malignant (clonal) proliferation of B- lymphocytes or T- lymphocytes which involves the lymph nodes, bone marrow and/or extranodal sites. "The mass was 1.5 by 1.2 by 0.9 cm with lymphoma cell infiltration to follicular epithelial cells (which were positive for thyroglobulin); B lymphocytes were positive for CD79a." (PMID 38791947, 2024). "Even more, thyroglobulin measurement in FNA specimens is particularly useful when cytology is inadequate or suspicious, as this case, where the cytology was suggestive of lymphoma." (PMID 39911757, 2025). "An ultrasound guided fine needle biopsy of this lymph node identified by I-131 SPECT/CT and FDG-F-18 PET/CT revealed lymphoma cells and was negative for thyroid tissue and thyroglobulin content." (PMID 24728254, 2014).
Nephropathy (6 papers, 2020 to 2024). A nonspecific term referring to disease or damage of the kidneys. "Presently, AITD-associated nephropathy is primarily diagnosed by thyroglobulin immunohistochemical staining, which shows an extremely low positive rate." (PMID 32425952, 2020).
nodular goiter (6 papers, 2011 to 2024). Goiter characterized by discrete tissue mass(es) that may or may not produce thyroid hormones. "In the groups of individuals having nodular goiter relapse and nodular goiter with rapid growth, the titer of anti-thyroglobulin autoantibodies was statistically lower compared to the group of individuals with nodular goiter and slow growth: 42.5% and 19.4%, respectively (р<0,05)." (PMID 33072219, 2020).
rheumatoid arthritis (6 papers, 2017 to 2024). A chronic, systemic autoimmune disorder characterized by inflammation in the synovial membranes and articular surfaces. "In a recent meta-analysis, patients with rheumatoid arthritis had a three times higher risk of having thyroid autoantibodies than healthy controls [thyroglobulin autoantibody (TgAb): OR 3.17 (2.24–4.49) and thyroglobulin autoantibody (TPOAb): OR 2.33 (1.24–4.39)]." (PMID 28824542, 2017).
toxic nodular goiter (6 papers, 2014 to 2024). "TSH: thyroid stimulating hormone; fT4: thyroxine; fT3: triiodothyronine; TRAB: TSH receptor antibody; Anti-TG: anti-thyroglobulin; Anti-TPO: anti-thyroid peroxidase; TMNG: toxic multinodular goiter." (PMID 31066760, 2019).
nephrotic syndrome (5 papers, 2017 to 2026). A collection of symptoms that include severe edema, proteinuria, and hypoalbuminemia; it is indicative of renal dysfunction. "In this study however, we enrolled all patients with nephrotic syndrome of which the majority (67.6%, 55 out of 70) had steroid sensitive nephrotic syndrome and as such might be less likely to lose protein (including thyroglobulin, thyroxine and TSH) in urine." (PMID 38373933, 2024).
thyroid dysgenesis (5 papers, 2014 to 2025). "Serum thyroglobulin levels close to zero suggest thyroid agenesis, low levels suggest thyroid hypoplasia, and high levels suggest dyshormonogenesis." (PMID 39857886, 2025).
acne (4 papers, 2021 to 2023). An inflammatory process of the sebaceous glands which is characterized by comedones, nodules, papules and/or pustules on the skin. "The risk analysis indicated that the presence of increased anti-TPO (2.91 times) and the association with anti-TG (4.36 times) doubles the risk of developing severe acne in patients with AIT." (PMID 33924808, 2021). "The risk analysis indicated that raised values of anti-TPO (2.91 times greater) correlated with high anti-thyroglobulin (TG) values (4.36 times greater) doubled the risk of developing severe acne in patients." (PMID 33924808, 2021). "The data analysis showed that the presence of increased anti-TPO (2.91 times) and the association with anti-TG (4.36 times) doubled the risk of developing severe acne in patients with AIT." (PMID 33924808, 2021). "The TSH and anti thyroidperoxidase (TPO) values did not influence the severity of the acne (p = 0.494; p = 0.111), while the anti-TG values were associated with severe acne (p = 0.007)." (PMID 33924808, 2021). "The results of the present study indicate increased incidence of AIT in the studied population with acne; 59.3% patients had high serum levels of anti-TG antibodies and 62.2% of anti-TPO antibodies." (PMID 33924808, 2021). "In 2017, Stewart and Bazergy determined a 24.5% prevalence of anti-TG antibodies, and 18% of the anti-TPO antibodies were found in adult women with acne, thus noting significantly higher values compared with the control group." (PMID 33924808, 2021).
allergies (4 papers, 2017 to 2024). "The α-Gal epitope is commonly present in bovine IgE-reactive proteins recognized by patients with meat allergy, and bovine thyroglobulin is considered a very good marker antigen for α-Gal allergy and a rich source this carbohydrate determinant." (PMID 36826022, 2023). "Two out of 10 and 6 of 29 patients examined were positive for anti-TG autoantibodies, 2 of 8 and 0 of 19 patients examined were positive for anti-TPO antibodies, and four and six had histories of allergies (due to drugs, foods, bees, or pollen) in periods A and B, respectively." (PMID 39280362, 2024).
athyreosis (4 papers, 2013 to 2025). Athyreosis is a form of thyroid dysgenesis characterized by complete absence of thyroid tissue that results in primary congenital hypothyroidism, a permanent thyroid deficiency that is present from birth. "A serum thyroglobulin concentration below the detection threshold is highly suggestive of athyreosis or a complete thyroglobulin synthesis defect (2|⊕⊕⊕)." (PMID 24446653, 2014). "In other cases, the absence of Tc-99 or I-123 allows the diagnosis of athyreosis or, in the presence of high doses of thyroglobulin, the diagnosis of mutations that inactivate the TSH receptor, NIS mutation, previous exposure to iodine or maternal anti-TSH antibodies." (PMID 40862110, 2025). "Of the 20 patients with a screening TSH level in the 17–20 range, at least one had athyreosis indicated by thyroid scan (thyroglobulin level was not measured), and 9 had a low free T4 values on confirmatory thyroid function testing, suggesting classical CH." (PMID 26839208, 2016). "Elevated thyroglobulin levels may suggest dyshormonogenesis, and absent levels suggest athyreosis." (PMID 40862110, 2025).
bone metastasis (4 papers, 2013 to 2023). Transfer of a neoplasm from its primary site to bones. "In the subgroup analysis, female, patients with lung-only metastasis, hand-foot skin syndrome (HFS), and thyroglobulin response ≥ 60% observed longer PFS (p = 0.038, 0.045, 0.035, and 0.000, respectively), while patients with bone metastasis had lower PFS (p = 0.035)." (PMID 37534207, 2023).
carcinoid (4 papers, 2021 to 2025). "Thyroglobulin, another common marker, is also often detected in the follicles of struma carcinoid, further confirming the thyroid tissue characteristics of the tumors." (PMID 41244794, 2025). "Strumal carcinoids exhibit positive staining with neuroendocrine markers (carcinoid component) and thyroglobulin and thyroid transcription factor (TTF1) (thyroid component)." (PMID 34917031, 2021). "As expected, immunohistochemical evaluation confirms the duality of the disease, with expression of specific markers both of thyroid (thyroglobulin, TTF1, calcitonin) and carcinoid (chromogranin A, synaptophysin, NSE and CD56)." (PMID 35528006, 2022).
Hyperbilirubinemia (4 papers, 2008 to 2025). An increased amount of bilirubin in the blood. "Findings included conjugated hyperbilirubinemia, elevated NT-proBNP, increased free T3 (fT3) and free T4 (fT4), a markedly decreased TSH level, and positive anti-thyroperoxidase (anti-TPO), anti-thyroglobulin (anti-TG), and anti-receptor TSH (TRAb) antibodies." (PMID 40551915, 2025).
metastasis (4 papers, 2014 to 2023). The spread or migration of cancer cells from one part of the body (where they first appeared) to another. "None of the present 1000 patients showed features suspicious for pulmonary metastasis such as increasing serum thyroglobulin or enlarging pulmonary nodules during follow-up." (PMID 32368954, 2020). "Of the remaining 4/14 Group 1 cases (Cases 11–14), 2/4 of patients with unifocal carcinoma and neck LN metastases at surgery developed a new neck LN metastasis (1 LTC) in one case, positive at SPECT/CT but occult at WBS, with undetectable thyroglobulin." (PMID 36428861, 2022). "All patients had elevated thyroglobulin or anti-thyroglobulin antibody levels, while three demonstrated metabolically active disease with positive FDG uptake on PET scan, and one patient with persistent radioactive iodine avid pulmonary metastasis 36 years after her last RAI treatment." (PMID 25316293, 2014).
myasthenia gravis (4 papers, 2010 to 2024). Myasthenia gravis (MG) is a rare, clinically heterogeneous, autoimmune disorder of the neuromuscular junction characterized by fatigable weakness of voluntary muscles. "It is also of interest to note that one of the NMOSD patients in our study also had myasthenia gravis, since acetylcholinesterase, one of the targets of autoantibodies in myasthenia gravis, has an extensive degree of homology with thyroglobulin." (PMID 28533776, 2017).
sarcoidosis (4 papers, 2021 to 2024). Sarcoidosis is a multisystemic disorder of unknown cause characterized by the formation of immune granulomas in involved organs. "This patient’s extreme elevation in thyroglobulin combined with inherent T‐regulatory cell dysfunction in sarcoidosis likely contributed to her rapid disease progression." (PMID 34631064, 2021). "Sarcoidosis patients have also been shown to have higher levels of thyroglobulin antibodies and/or thyroid peroxidase antibodies compared to control subjects, although the pathogenetic role of these antibodies in the association between sarcoidosis and autoimmune thyroid disease is unknown." (PMID 35441568, 2022). "Interestingly, earlier we reported by immunoenzyme ELI-test elevated levels of autoantibodies to thyroglobulin (+59.1 ± 6.8% compared to average autoimmunoreactivity) in TB patients, but not in lung sarcoidosis." (PMID 39765749, 2024). "﻿The pathophysiologic and clinical significance of anti-thyroglobulin autoantibodies in patients with sarcoidosis is not clear, but it may be interpreted as a non-specific feature of a systemic autoimmune activation, characteristic of sarcoidosis." (PMID 33599943, 2021).
Thrombocytopenia (4 papers, 2022 to 2025). A reduction in the number of circulating thrombocytes. "Laboratory investigations revealed intermittent mild leucopenia and thrombocytopenia and positive anti-thyroglobulin antibodies." (PMID 39871364, 2025).
vitamin A deficiency (4 papers, 2023 to 2025). Deficiency of vitamin A due to malnutrition, malabsorption, or dietary lack. "It has been observed that vitamin A deficiency damages the formation of thyroglobulin, which is a protein precursor of THs." (PMID 37305054, 2023). "Vitamin A deficiency is associated with altered TSH secretion, impaired iodothyronine coupling, reduced thyroglobulin synthesis, and impaired iodine uptake." (PMID 38337667, 2024).
amyloidosis (3 papers, 2021 to 2024). A disorder characterized by the localized or diffuse accumulation of amyloid protein in various anatomic sites. "Antibodies anti-thyroid peroxidase, anti-thyroglobulin, and anti-TSHR were negative and amyloidosis was diagnosed on surgical sample of total thyroidectomy." (PMID 34063105, 2021).
Ataxia (3 papers, 2017 to 2021). Ataxia refers to impaired coordination of voluntary muscle movement. "In one such study, where persistent cerebellar ataxia was associated with elevated levels of autoantibodies against thyroglobulin and thyroperoxidase, the authors concluded that the most likely cause of the cerebellar degeneration in the patients was autoimmune attack." (PMID 28533776, 2017). "A neurological examination revealed nystagmus, intention tremor, and ataxia, and anti-thyroid peroxidase and anti-thyroglobulin levels were found to be elevated." (PMID 33477892, 2021).
Cirrhosis (3 papers, 2022 to 2024). A chronic disorder of the liver in which liver tissue becomes scarred and is partially replaced by regenerative nodules and fibrotic tissue resulting in loss of liver function. "Higher thyroglobulin antibody titers were reported in non-alcoholic liver disease and cirrhosis." (PMID 38152395, 2023).